IL26 (interleukin 26)
Diseases named in the same sentence as IL26 in open-access papers (continued):
Sharing a sentence is not in itself a finding about the gene and the disease.
infection (continued). "Studies have shown that the increase in IL-26 after infection may promote the release of aggregated HBP from neutrophils." (PMID 39724075, 2024). "Thus, the frequency of T cells expressing IL-10, IL-19, IL-24 and IL-26 are all decreased upon curative treatment, in contrast to that seen in those who continued to harbor infection." (PMID 24699268, 2014). "Therefore, the viruses or Colo-205 target cells were pre-incubated with IL-26 and subsequently used for infection because Colo-205 cells are known to express the functional IL-26R." (PMID 23875025, 2013). "Similarly to the IL-26-dependent enhanced VSV infection, the IL-26-dependent inhibition of HCMV-infection of fibroblasts was partially neutralized with the anti-IL-26 serum, in contrast to pre-immune serum." (PMID 23875025, 2013). "Consequently, the HCMV titers from IL-26-treated fibroblasts were about ten-fold lower than the titers reached with medium or IL-2 as control on d 4, 5, and 6 post infection." (PMID 23875025, 2013). "Furthermore, IL-26 is able to directly kill Mtb and decrease the infection rate in macrophages." (PMID 33057074, 2020). "Thus, IL-26 modulates the infection and replication of different virus species differentially." (PMID 23875025, 2013). "Thus, IL-26 differentially modulates the infection by different enveloped viruses." (PMID 23875025, 2013). "Moreover, IL-26 potentiates neutrophil chemotaxis induced by IL-8 or the bacterial compound N-Formylmethionyl-leucyl-phenylalanine in vitro, implying that IL-26 may potentiate neutrophil mobilization towards the source of inflammation and infection." (PMID 35501858, 2022). "VSV supernatant was pre-incubated with IL-26 or GST (1 μg/ml) as control protein and supernatants were collected 2-12 h after the infection of Colo-205 cells (MOI = 0.01)." (PMID 23875025, 2013). "Whereas IL-26 induced a strong enhancement of VSV binding, infection, and replication, the HCMV-infection of IL-26-treated human fibroblasts was inhibited, and HSV-1 infection was not influenced." (PMID 23875025, 2013). "In contrast to VSV, the infection of HCMV was inhibited by IL-26-pre-incubation (5 or 25 μg/ml) of HCMV or primary human fibroblasts and subsequent infection with HCMV at MOI = 0.003 after 5 d." (PMID 23875025, 2013). "In order to define the mechanism of the IL-26 effect on VSV infection more closely, different infection conditions were compared." (PMID 23875025, 2013). "In the medium from the incubated cells at the 72nd hour post-infection, there were no detectable amounts of IL-26, or IL-2, IL-5, IL-13, IL-22, GM-CSF, basic fibroblast growth factor, and macrophage inflammatory protein-1α." (PMID 41516201, 2025). "In contrast, IL-26 does not modulate the infection of the epithelial cell line Vero by Herpes virus simplex 1 (HSV-1)." (PMID 30809226, 2019). "HT-29 cells with or without functional IL-26R showed similar IL-26-inducible VSV-infection rates as Colo-205 cells and non-transfected parental HT-29 cells, excluding an essential role of the IL-20R1 chain." (PMID 23875025, 2013). "The numbers of HSV-1-infected primary fibroblasts on d 1 and 2 post infection were not relevantly altered by IL-26 in a similar experimental setup." (PMID 23875025, 2013). "Treatment of filarial infection and consequent cure resulted in significantly decreased frequencies of CD4+ T cells expressing IL-10, IL-19, IL-24 and IL-26 after parasite-antigen stimulation whereas those who continued to harbor infection did not exhibit reduction in these frequencies." (PMID 24699268, 2014). "Therefore, we speculated for antiviral properties of IL-26 and used the rhabdovirus vesicular stomatitis virus (VSV) and the herpesviruses human cytomegalovirus (HCMV) and herpes simplex virus type-1 (HSV-1) as model viruses for infection studies." (PMID 23875025, 2013). "In contrast, the infection of IL-26-treated human fibroblasts with HCMV was inhibited and the infection by HSV-1 was not altered by IL-26." (PMID 23875025, 2013).
bacterial infection (10 papers, 2016 to 2025). "This study underscores the potential of using IL-26 as an agent to fight off bacterial infections in the gut." (PMID 41125850, 2025). "Our findings establish that IL-26 protects the gut from bacterial infections, and that this correlates with increased bacterial loads and DNA damage as well as an impaired immune response." (PMID 41125850, 2025). "IL-26 displays direct antimicrobial effects and immunomodulatory capabilities in the defense against bacterial infections." (PMID 41516201, 2025). "Recently, IL-26 was regarded as a critical cytokine for extracellular DNA-induced inflammation and bacterial infection." (PMID 32290250, 2020). "Given that increased susceptibility to bacterial infections is also a morbidity amongst long-term smokers, with or without COPD, our finding supports the idea that local IL-26 is involved in the alterations of innate immunity in these subjects." (PMID 29780024, 2018). "Furthermore, IL-26 protected the gut from bacterial infection by regulating bacterial loads, DNA damage, and cytokine expression." (PMID 41125850, 2025). "The cytokine IL-26 is abundantly expressed in healthy human airways during stable conditions, and its expression is enhanced during bacterial infection, whereupon IL-26 can contribute to airway host defense via its neutrophil-mobilizing and antibacterial properties." (PMID 37234157, 2023). "On the other hand, IL-22 and IL-26 expressions were shown to be higher in transgenic epinecidin-1 zebrafish 12 h after bacterial infection, suggesting that both IL-22 and IL-26 may be the key immune mediators released by transgenic zebrafish muscle." (PMID 31824449, 2019). "Furthermore, IL-26 produced by CD68+ alveolar macrophages and Th17 cells strengthens antimicrobial defense in the lungs by promoting neutrophil recruitment to sites of bacterial infection." (PMID 41516201, 2025). "Consistently, IL-26 produced by CD68+ alveolar macrophages and Th17 cells has been shown to strengthen pulmonary antimicrobial immunity by promoting neutrophil recruitment to sites of bacterial infection." (PMID 41516201, 2025). "This consistent finding indicates that there is relatively rapid release of prestored IL-26 rather than enhanced gene transcription during bacterial infection in human lungs." (PMID 34777376, 2021). "Third, the absence of IL-26 in mice has greatly hindered our progress in understanding the antimicrobial functions of IL-26, its regulation, and therapeutic applications for various bacterial diseases." (PMID 27337042, 2016).
cancer (10 papers, 2017 to 2025). A tumor composed of atypical neoplastic, often pleomorphic cells that invade other tissues. "In all these examples, elevated IL-26 levels are directly associated with cancer phase or progression." (PMID 41516201, 2025). "The purpose of this review is to summarize recent findings on the potential pathological roles of IL-26 in inflammatory disorders and cancer." (PMID 41516201, 2025). "Many other investigators have demonstrated the promising role of IL26 with immunotherapy in treating cancers." (PMID 34621670, 2021). "Although IL-26 may enhance type I interferon secretion and presumably activate dormant cancer stem cells, its reduced expression may limit drug efficacy and exacerbate survival outcomes." (PMID 41516201, 2025). "The contradictory role of IL-26 in cancer may be partially explained by its essential role in autophagy." (PMID 41516201, 2025). "In addition, IL-26 has a role in the development of other cancers including gastric cancer and hepatocellular carcinoma, while little is known about its function in breast cancer." (PMID 34021125, 2021). "Taken together, the existence of such non-metastatic and non-proliferative associations of IL-26 and JAK/STAT signaling further complicates their potential role in cancer progression, cellular proliferation, and apoptosis in the context of the TME." (PMID 41516201, 2025). "The role of IL-26 in cancer has not been studied extensively, but its involvement in the progression of human TNBC has recently been reported." (PMID 40806452, 2025). "Additionally, an analysis of IL-26 serum levels in 302 GC patients across various stages (I, II, III, and IV) demonstrated that IL-26 levels were significantly higher in patients with malignant tumors compared to those with benign conditions." (PMID 40806452, 2025). "While IL-26 is involved in cancer biology, the precise molecular mechanisms associated with this process, including the identification of the functional receptor of IL-26 in cancer cells and its downstream signaling events, are not yet clarified." (PMID 34021125, 2021). "The five EV-dependent regulated genes whose expression changes were prevented by importazole (i.e. ghrelin, IL-26, IL-17B, Casp1 and CCL5) may be relevant for the pro-tumorigenic activity of cancer EVs." (PMID 28129640, 2017).
infectious disease (2 papers, 2021 to 2022). A disorder directly resulting from the presence and activity of a microbial, viral, or parasitic agent in humans. "IL-26 has recently emerged as a DNA-shuttling molecule involved in the pathophysiology of chronic inflammatory disorders as well as in various infectious diseases, both viral and bacterial." (PMID 34054830, 2021). "The function of IL-26 as promoting DNA sensing in an immunostimulatory manner has been attracting attention in the field of pathological conditions regarding chronic inflammatory disorders or infectious diseases." (PMID 36311716, 2022).
immune diseases (1 paper, 2020). "Among 42 cytokines measured, significant changes were observed for only 4 cytokines (IL-13, IL-17, IL-26, MIP-1β), three of which were reported as overexpressed in auto-immune diseases (IL-17, IL-13, IL-26)." (PMID 32429322, 2020).
IL26 also shares sentences with these, for which no sentence is quoted: Granuloma (2 papers); inflammation (2); non-small cell lung carcinoma (2); osteoarthritis (2); allergic asthma (1); allergic disease (1); ankylosing spondylitis (1); bladder cancer (1); bullous pemphigoid (1); Chronic colitis (1); chronic hepatitis C (1); Down syndrome (1); fibrosarcoma (1); food allergy (1); gastrointestinal disease (1); gastrointestinal infections (1); glioma (1); inflammatory skin disease (1); intestinal diseases (1); lymphoma (1); metabolic disorder (1); pernicious anemia (1); prostate carcinoma (1); Proteinuria (1); psoriasis vulgaris (1); psoriatic arthritis (1); psychiatric disorder (1); synovitis (1); trisomy 21 (1); Uterine leiomyoma (1).
A further 1 disease shares a sentence with IL26 in 1 paper.